DAXX (death domain associated protein)
Diseases named in the same sentence as DAXX in open-access papers (continued):
Sharing a sentence is not in itself a finding about the gene and the disease.
breast carcinoma (11 papers, 2016 to 2025). "Hussien Marwa Tet al.’s study demonstrated that the low expression of DAXX was associated with the poor prognosis in breast cancer, indicating that the mechanism-mediated by DAXX as a target may have the potential to treat different types of cancer." (PMID 39669558, 2024). "In summary, combining the previous studies with our study can enhance the persuasiveness of JAK2 and DAXX as candidate genes for breast cancer treatment." (PMID 39669558, 2024). "This study aims to evaluate the prognostic significance of telomere length (TL) and its association with DAXX and ATRX proteins in breast cancer (BC)." (PMID 32856116, 2020). "Death domain-associated protein 6 (DAXX) was recently identified as a NOTCH target, whose levels were significantly increased in human breast cancers that were treated with endocrine therapy after a short treatment with a gamma secretase inhibitor." (PMID 32210163, 2020). "Estradiol, while it stimulates proliferation of ER+ breast cancer cells, is a potent stabilizer of the DAXX protein and repressor of NOTCH4 and other stem cell genes thus inhibiting TICs." (PMID 32864429, 2020). "Then, we developed a risk prognostic model based on expression levels of PIK3CA, SESN3, ANXA5, MYD88, DPP4, DAXX, and CRIP1 to predict clinical outcomes in patients with breast cancer." (PMID 41357233, 2025). "The expression levels of MYD88, DAXX and ANXA5 were significantly upregulated in the control samples compared to breast cancer samples." (PMID 41357233, 2025). "Mechanistically, DAXX bind to the RAD51 promoter thereby repressing the function of RAD51 and resulting in the inhibition of breast cancer metastasis." (PMID 32257110, 2020). "Unlike other histone chaperones DAXX is found to be downregulated in breast cancer metastasis." (PMID 32257110, 2020).
glioma (11 papers, 2013 to 2024). A benign or malignant brain and spinal cord tumor that arises from glial cells (astrocytes, oligodendrocytes, ependymal cells). "He then shared several case studies on ATRX/DAXX mutations in glioma molecular classification and subsequent treatment." (PMID 28797870, 2017). "The recent findings of somatic mutations in key regulatory genes (H3.3, ATRX and DAXX) highlight the importance epigenetic alterations have in the development of glioma." (PMID 22771539, 2013). "Point mutations in histone variant H3.3 (H3.3K27M, H3.3G34R) and the H3.3-specific ATRX/DAXX chaperone complex are frequent events in pediatric gliomas." (PMID 38066546, 2023). "We found an overexpression of DLGAP5, NEK2, and PBK, while the expression of SF1, PTEN, ATRX, and DAXX was downregulated in tumor tissues as compared to normal tissues of the patients with glioma." (PMID 35095717, 2021). "In summary, our data support an important role for ATRX/DAXX loss and acquisition of ALT with an aggressive biology in NF1-associated gliomas, as well as a molecular subset of NF1-associated MPNSTs." (PMID 31462295, 2019). "DAXX knockdown in PTEN-WT cells slightly affected cell proliferation in glioma cells, which is perhaps related to other molecular mechanisms associated with DAXX50." (PMID 28497778, 2017). "Moreover, DAXX mutations are not generally found in adult low-grade gliomas, indicating that DAXX-independent mechanisms of mutant ATRX may play a role in the phenotype of these tumour cells." (PMID 35382567, 2022). "All of the glioma lines assessed retain expression of both ATRX and DAXX, as assessed by immunoblotting and immunohistochemistry, while U2-OS, a well-characterized ALT-positive osteosarcoma cell line harboring an ATRX deletion, lacks ATRX expression." (PMID 30226859, 2018). "Pulldown assays using purified recombinant proteins and total protein lysates from glioma cells that expressed different endogenous PTEN and DAXX levels demonstrated that PTEN can physically interact with DAXX." (PMID 28497778, 2017). "Having established that DAXX disruption inhibits tumour growth and increases survival in GBM-PDX models, we next examined if DAXX gene expression was altered in different human gliomas." (PMID 28497778, 2017).
gastric cancer (10 papers, 2020 to 2025). A primary or metastatic malignant neoplasm involving the stomach. "The accumulation of death domain-associated protein (DAXX) in the nucleus of tumors is associated with the poor prognosis of gastric cancer." (PMID 37777749, 2023). "Liu and colleagues created a synthetic circRNA to sponge miR-21 and found that the inhibition of miR-21 through this method could suppress gastric carcinoma cell proliferation by downregulating death domain-associated protein DAXX." (PMID 36139366, 2022). "DAXX is a transcription repressor that has been implicated in several types of cancers, but its role in the development of gastric cancer remains unknown." (PMID 32203224, 2020). "The expression levels of cytoplasmic DAXX have been found to correlate with enhanced survival outcomes, while elevated levels of nuclear DAXX indicate a poorer prognosis in gastric cancer." (PMID 40271196, 2025). "DAXX-regulated genes are important effectors in cell death, survival and tumorigenesis, so the expression level of DAXX is increased in several cancer types including prostate, ovarian and gastric cancer." (PMID 36911524, 2023). "For example, a synthetic circRNA that sponges miR21 caused the upregulation of the death domain-associated protein (DAXX) and demonstrated anti-proliferative activity in gastric cancer." (PMID 35269953, 2022). "DAXX overexpression inhibited the growth of gastric cancer through downregulating snail family transcriptional repressor 3 (SNAI3), a key inducer of EMT, by recruiting HDAC-1 into the nucleus." (PMID 35087762, 2021). "The upregulation of DAXX in gastric cancer cells inhibited proliferation, migration, invasion, and epithelial-mesenchymal transition (EMT)." (PMID 35087762, 2021). "DAXX is downregulated in advanced gastric cancer and human colon adenocarcinoma cells, lung cancer, and PanNETs." (PMID 35087762, 2021). "Taken together, our data provide new insights into the role of DAXX as a tumour suppressor in gastric cancer, and suggest that upregulation of DAXX can overcome chemoresistance." (PMID 32203224, 2020). "We for the first time demonstrated that DAXX functions as a tumour suppressor in gastric cancer by inhibiting stem cell growth and EMT." (PMID 32203224, 2020). "DAXX overexpression in gastric cancer cells inhibited migration, invasion and epithelial– mesenchymal transition (EMT)." (PMID 32203224, 2020). "However, altering the subcellular localizations of DAXX results in different biological functions, and we also found that its nuclear/cytoplasmic ratio (NCR) was associated with poor prognosis in gastric cancer (GC)." (PMID 32641734, 2020). "However, the expression of DAXX was decreased in advanced gastric cancer samples." (PMID 35087762, 2021). "Overexpression of DAXX has been observed in various tumour types, including prostate cancer, ovarian cancer, oral squamous cell carcinoma (OSCC) and gastric cancer." (PMID 40987316, 2025). "The expression of DAXX inversely correlates with that of cancer stem cell markers CD44 and Oct4 in gastric cancer lines." (PMID 32203224, 2020). "Both DAXX and HDAC-1 were detected in the proteins pulled down by the HA antibody in gastric cancer cells overexpressing DAXX, suggesting that DAXX and HDAC-1 are physically associated within these cells." (PMID 32203224, 2020). "The mechanisms by which DAXX induces downregulation of SNAI3 in gastric cancer cells are not clear." (PMID 32203224, 2020).
metastatic disease (9 papers, 2017 to 2025). "As such, in retrospective studies, ALT and loss of ATRX and DAXX have been shown to be strong prognostic biomarkers of recurrence or metachronous metastatic disease in sporadic NF-PanNETs." (PMID 39954168, 2025). "Other recent studies have confirmed in a large series of PanNET patients that alternative lengthening of telomeres (ALT) and loss of DAXX/ATRX predict metastatic disease and poor survival in patients with PanNET." (PMID 29156578, 2017). "In metastatic disease, DAXX/ATRX loss seems to be associated with longer survival." (PMID 35326628, 2022). "Our data suggest that MEN1 alterations are an early event in tumorigenesis and that ATRX/DAXX variants may be later events in disease progression or occur more frequently in patients presenting with metastatic disease." (PMID 29212165, 2017). "In our study, we integrate large publicly available datasets of PANETs to show a remarkably conserved MEN1- and DAXX/ATRX-driven metastatic disease progression." (PMID 32345369, 2020). "According to these observations, it was concluded that ALT and DAXX/ATRX loss in PanNET was associated with reduced survival and seems to play an important role in driving metastatic disease." (PMID 29156578, 2017). "Recent studies indicate that loss of DAXX/ATRX expression and alternative lengthening of telomeres predict metastatic disease and poor survival in PanNET patients." (PMID 29156578, 2017). "Therefore, loss of ATRX/DAXX protein and ALT in primary PanNET is a strong prognostic biomarker of recurrence and/or development of metachronous metastatic disease." (PMID 37190157, 2023). "However, in subsequent metastatic disease (Mets2), methylation decreased to lower levels for the specific DMRs identified (which included probes for DAXX, LTB4R & CIDEB) in both cases." (PMID 33436720, 2021). "Importantly, ATRX and DAXX mutations do not appear to initiate tumor development but rather occur at a later stage where they are associated with progression to metastatic disease and poor survival rates." (PMID 39954168, 2025). "However, ATRX/DAXX protein loss is not the initiating genomic alteration but rather occurs at a later stage in the development of the primary NF-PanNET that is associated with the progression to metastatic disease." (PMID 37190157, 2023).
neuroendocrine tumors (9 papers, 2018 to 2026). "In a different study, MEN1 and DAXX were shown to repress the expression of the membrane metalloendopeptidase (MME) and mutations in MEN1 or DAXX result in loss of this repression leading to neuroendocrine tumor proliferation." (PMID 30315258, 2018). "DAXX was expressed in 100% of neuroendocrine tumor tissue, and no patient showed loss of IHC expression of this marker." (PMID 30627226, 2018). "Furthermore, we observe distinct drivers which are enriched in somatic aberrations in pancreatic (MEN1, ATRX, DAXX, DMD and CREBBP) and midgut-derived neuroendocrine tumors (CDKN1B)." (PMID 34326338, 2021).
osteosarcoma (9 papers, 2018 to 2025). A usually aggressive malignant bone-forming mesenchymal neoplasm, predominantly affecting adolescents and young adults. "Abnormal expression of ATRX or DAXX tended to be more prevalent in the osteosarcoma cell lines and was associated with significantly higher C-circle and APB scores." (PMID 41436729, 2025). "While ALT correlates strongly with ATRX mutations in osteosarcoma, DAXX mutations are frequently observed in pancreatic neuroendocrine tumors (PanNETs) and correlate with poorer prognosis." (PMID 37107548, 2023). "We confirmed protein expression of ATRX and DAXX in G292 by western blot, revealing normal ATRX protein expression but aberrant size of DAXX protein in comparison with other osteosarcoma cell lines." (PMID 30872698, 2019). "Here we characterize an osteosarcoma cell line, G292, with wild-type ATRX but a unique chromosome translocation resulting in loss of DAXX function." (PMID 30872698, 2019). "ATRX/DAXX mutations associated with ALT telomere maintenance are most frequently observed in liposarcomas, adult gliomas, pancreatic neuro-endocrine tumors, and osteosarcomas." (PMID 37107548, 2023). "When the loss of ATRX and DAXX is detected, the chance of the tumor being ALT positive varies from 83% in leiomyosarcoma to 100% in osteosarcoma and liposarcoma, suggesting that mutation analysis of the ATRX and DAXX gene is a reliable predictor of the ALT positivity in certain cancers." (PMID 34069193, 2021). "To confirm this result, we analyzed the seven osteosarcoma tumor samples for ATRX, DAXX, SMARCAL1, H3.3, and SLX4IP protein expression by immunoblotting." (PMID 31447390, 2019). "Using immunofluorescence imaging, we assayed the localization of ATRX and DAXX in G292 and the TERT + osteosarcoma line SJSA1." (PMID 30872698, 2019). "To further validate the transcript fusion between DAXX and KIFC3 in this sample we isolated RNA from both G292 cells and a telomerase positive osteosarcoma cell line, SJSA1." (PMID 30214690, 2018).
promyelocytic leukemia (7 papers, 2010 to 2020). "ATRX has been shown to exhibit a physical interaction with the transcriptional regulatory factor death domain associated protein (DAXX) at promyelocytic leukemia nuclear bodies (PML's) in both human and murine somatic cells." (PMID 20885787, 2010). "There is also evidence for ATF7IP2 and ATRX transcriptional activation role, through SP1 and DAXX interaction, in promyelocytic leukemia nuclear bodies." (PMID 28293299, 2017). "BNRF1 wt co-localized strongly with DAXX at punctate subnuclear structures previously shown to be PML-NBs (promyelocytic leukemia-nuclear bodies)." (PMID 27581705, 2016). "Promyelocytic leukemia-mediated regulation of DAXX function could be particular relevant in the central nervous system (CNS), given the roles played by the two proteins in this context." (PMID 23760585, 2013). "Notably, the EBV tegument protein BNRF1 targets ATRX and DAXX for sequestration in promyelocytic leukemia (PML) bodies at this time point, suggesting that HIRA and newly induced CAF1 may be responsible." (PMID 33109754, 2020).
viral infection (7 papers, 2011 to 2020). "Death domain associated protein (Daxx) is a highly conserved nuclear protein playing an important roles in the transcriptional control, carcinogenesis, resistance to virus infection and so on." (PMID 24398161, 2014). "Our results suggest that DAXX may have ATRX-independent functions during viral infection." (PMID 30465651, 2018). "Several PML-NB components like PML itself, SP100, DAXX, and ATRX are bona fide restriction factors for viral infection, undermined by the observation that PML-NB components like PML, Sp100, and DAXX are induced by interferon." (PMID 31500286, 2019). "They revealed that PML and DAXX knock-down leads to a reduction in HPV18 transcription, while SP100 behaves as a repressor of viral infection." (PMID 26148509, 2015).
sarcoma (6 papers, 2017 to 2023). A usually aggressive malignant neoplasm of the soft tissue or bone. "Here we sought to investigate the genomic determinants of high telomeric content beyond the canonical ATRX/DAXX alterations within our sarcoma dataset." (PMID 37709802, 2023). "ALT activation is described in sarcoma, astrocytoma, neuroblastoma, and carcinoma cases as well as CM and is related to functional loss of ATRX and/or histone H3.3 chaperone DAXX." (PMID 37629169, 2023). "In general, mutations affecting DAXX are more common in PanNET, whereas those affecting ATRX are markedly prominent in sarcomas." (PMID 30871494, 2019). "In our dataset, only 12.3% of sarcomas harbored ATRX/DAXX alterations." (PMID 37709802, 2023). "DAXX and ATRX may be also mutated in different types of sarcomas." (PMID 30871494, 2019). "Loss of DAXX (death-domain associated protein) expression has not yet been observed in any sarcoma." (PMID 28484590, 2017). "Differentially methylated regions and genes were detected, not been previously implicated in sarcoma progression, including at PTPRN2 and DAXX in LMS, WT1-AS and TNXB in SS, VENTX and NTRK3 in pleomorphic RMS and MEST and the C14MC / miR-379/miR-656 in MFS." (PMID 33436720, 2021).
colon cancer (5 papers, 2018 to 2025). "In colon cancer cells, DAXX was down-regulated, and the interaction between DAXX and Tcf4 was strongly associated with the proliferation of colon cancer cells, indicating that DAXX functions as a suppressor of tumor proliferation." (PMID 31942198, 2020). "Here, we report that in human colon cancer cells, the H3.3 chaperones HIRA and DAXX promote ectopic CENP-A deposition." (PMID 30365520, 2018).
lung carcinoma (5 papers, 2016 to 2025). "In another study, DAXX functions as a tumor suppressor by inhibiting the HIF-1a/HDAC1/Slug axis in hypoxia-induced lung cancer cells." (PMID 35087762, 2021).
neuroblastoma (5 papers, 2018 to 2024). Neuroblastoma (NB) is the most common solid, extracranial childhood tumor. "Mutations in the chromatin remodeler ATRX and its partner DAXX are strongly associated with ALT while MYCN amplification is observed in telomerase-dependent/ALT-negative neuroblastomas." (PMID 38837897, 2024). "The neuroblastoma samples were previously evaluated for ATRX and DAXX mutations, and MYCN amplification." (PMID 38837897, 2024). "Consistent with this idea, we observed that knocking down DAXX reduced ATRX protein levels in neuroblastoma cells." (PMID 33627664, 2021). "Reduced ATRX protein levels in ALT ATRX wild-type neuroblastoma could be explained by the reduced DAXX protein levels, which we specifically observed in this subgroup of tumors." (PMID 33627664, 2021). "Integrating proteomic profiling revealed reduced ATRX/DAXX protein complex abundance as a recurrent event in ALT-positive neuroblastoma, which could often not be explained by mutations in these genes." (PMID 33627664, 2021). "To investigate if reduced DAXX levels could explain ATRX downregulation at the protein level, we knocked-down DAXX in the ALT-negative neuroblastoma cell line NBL-S and observed that ATRX protein levels were indeed reduced after 96 h." (PMID 33627664, 2021).
neuroendocrine carcinoma (5 papers, 2018 to 2025). A malignant neuroendocrine neoplasm composed of cells containing secretory granules that stain positive for NSE and chromogranin.
schizophrenia (5 papers, 2012 to 2022). A major psychotic disorder characterized by abnormalities in the perception or expression of reality. "Most strikingly, we found that both DMP (such as CSMD1) and DMRs (DAXX and ARL4D) are annotated to genes related to neurological disorders such as ASD, PTSD and schizophrenia, pointing out to the potential risk of these children to suffer from these disorders." (PMID 35836289, 2022).
astrocytomas (4 papers, 2017 to 2023). "By using the REMBRANDT and TCGA databases we found a statistically significant (P<0.0001) upregulation of DAXX expression in GBMs, oligodendrogliomas and astrocytomas in comparison with normal brain." (PMID 28497778, 2017).